PVT1 (Pvt1 oncogene)
Diseases named in the same sentence as PVT1 in open-access papers (continued):
Sharing a sentence is not in itself a finding about the gene and the disease.
tumor (continued). "At the same time, with the discovery of PVT1-encoded miRNAs, an increasing number of studies have revealed that these miRNAs also participate in the regulation of tumor progression." (PMID 31380270, 2019). "These contradictory tumor-suppressing effects caused by the inhibition of PVT1 through miR-1204, miR-1207-3p, and miR-1207-5p warrant further investigation." (PMID 31380270, 2019). "Existing studies have shown that PVT1 is overexpressed in a variety of tumors, and its expression is closely associated with tumor proliferation and apoptosis, invasion and metastasis, angiogenesis, and drug resistance." (PMID 31380270, 2019). "PVT1 itself has been implicated in cell proliferation, apoptosis, lymph node invasion, metastasis, and tumor prognosis." (PMID 31766781, 2019). "PVT1, which is associated with tumor progression and predicts recurrence, directly interacted with STAT3, increased its protein stability, and inhibited poly-ubiquitination and proteasome-dependent degradation." (PMID 31028131, 2019). "Higher PVT1 expression level is associated with tumor progression and predicts recurrence in HCC patients." (PMID 29047230, 2017). "As to the TCGA data, highly PVT1 expression was associated with advanced T-stage and tumor–node–metastasis (TNM) stage, histologic grade, and distant metastasis." (PMID 29156724, 2017). "This co-dependence was further supported by the association of both pvt1 and myc duplication in almost every tumor bearing myc amplification." (PMID 26992233, 2016). "For example, the upregulation of PVT1 is associated with the inhibition of apoptosis and affects the apoptotic response of immune cells by regulating mitochondrial function, thus, helping tumor cells evade immune clearance." (PMID 40149989, 2025). "PVT1, a long non-coding RNA frequently upregulated in diverse cancers, is intimately linked with the proliferative, invasive, and metastatic propensities of tumor cells." (PMID 39286016, 2024). "PVT1 enhances tumor progression and metastasis and is associated with worse ccRCC outcomes." (PMID 36847128, 2023). "Numerous tumor associated lincRNAs were identified, such as PVT1, HIF1A-AS1 and MIAT." (PMID 36071454, 2022). "PVT1 participates in various tumor drug resistance and is associated with hypoxia conditions." (PMID 35256612, 2022). "High PVT1 expression is associated with tumor progression and poor prognosis." (PMID 34922601, 2021). "The tumorigenic potency of PVT1 could be abrogated by miR-543 overexpression, and loss of PVT1 is associated with inhibition of growth, increased apoptosis, and decreased tumor size." (PMID 34527584, 2021). "Interestingly, the miR-200 family is generally associated with tumor suppressors and oncogenic lncRNAs such as PVT1 silence miR-200a and miR-200b to enhance NSCLC tumorigenesis." (PMID 32629922, 2020). "The oncogenic role of PVT1 and circPVT1 has also been linked to their function as competing endogenous RNA (ceRNA) through binding of tumor suppressor microRNAs and circPVT1 could serve as sponges for RNA-binding proteins (RBPs)." (PMID 32228602, 2020). "PVT1 and miR-194-5p are novel and important tumor biomarkers, and could be some underlying diagnostic biomarkers and remedial targets for malignant BC in the future." (PMID 33188158, 2020). "Interestingly, a recent study has confirmed the tumor-inhibitory role of the PVT1 promoter; the underlying mechanism is that the PVT1 promoter inhibits Myc transcription from the same chromosome through promoter competition." (PMID 31497532, 2019). "Moreover, the co-culturing of BMSC-EXOsi-PVT1 and ERG-overexpressing MNNG/HOS cells (MNNG/HOSAd-ERG) restored the defect of tumor malignancy caused by the co-culturing of BMSC-EXOsi-PVT1 and MNNG/HOS cells." (PMID 31699956, 2019). "The lncRNA PVT1 (plasmacytoma variant translocation 1) has been reported to be up-regulated in a variety of malignancies and can promote tumor cell proliferation, migration and tumor growth and metastasis." (PMID 30894138, 2019).
tumor (continued). "Interestingly, we observed that circ-PVT1 silencing suppressed GC cell growth, and knockdown of circ-PVT1 elevated PTX-caused anti-tumor effect in vivo, meaning that chemoresistance of circ-PVT1 was validated on GC xenografts in nude mice." (PMID 31793989, 2019). "Furthermore, through comparing the clinical information of 121 patients, we found that PVT1 expression was linked to tumor size, number, grade and stage." (PMID 30008615, 2018). "A number of noncoding RNAs such as urothelial cancer associated 1 (UCA1), MALAT1, H19, and plasmacytoma variant translocation (PVT1) have been implicated in the promotion of metastasis of tumour cells, but evidence for a more direct role of these RNAs in this process is still lacking." (PMID 30296263, 2018). "Interestingly, besides PVT1, only 5 other genes showed a strong misregulation consistently linked with clinical outcome and tumor features in KIRC (phenotype permutation p-value < 0.001)." (PMID 27366943, 2016). "The tumor tissue expression level of PVT1 has been reported to be associated with the tumor size." (PMID 27495068, 2016). "Strikingly short-term knockdown of Pvt1 (within 96 h of shRNA administration) was sufficient to cause a significant reduction in tumor burden, suggesting that transient dynamic changes occurring during disease progression may be adequate at impacting disease outcomes." (PMID 35820706, 2022). "Importantly, PVT1 has been associated with poorer prognosis and regulation of tumor growth in PCa." (PMID 31766781, 2019). "Furthermore, shRNA-mediated loss of PVT1 function also resulted in a reduced tumor growth in vivo." (PMID 31781490, 2019). "A greater TNM stage, a larger tumor, and a lower OS were all attributed to the upregulation of PVT-1 in human NSCLC tissues." (PMID 39912974, 2025). "While the PVT1 locus contains oncogenic MYC enhancers, PVT1 transcription was shown to serve a tumor suppressive role by curbing MYC transcription." (PMID 40743223, 2025). "Efforts to dissociate RNA and DNA-based mechanisms unexpectedly revealed that the PVT1 lncRNA harbors tumor suppressive elements that limit MYC levels." (PMID 40743223, 2025). "PVT1 (Plasmacytoma Variant Translocation 1) facilitates the stabilization of the MYC oncogene, which in turn enhances the proliferation of tumor cells and makes them resistant to platinum chemotherapy." (PMID 41155343, 2025). "Reports indicate that the oncogenic lncRNA PVT1, acting as a ceRNA or molecular sponge, downregulates miRNA, thereby promoting tumor development and chemotherapeutic drug resistance." (PMID 40191723, 2025). "The lncRNA PVT1 enhances the immunosuppressive effects of MDSCs by regulating their differentiation and function, thereby promoting tumor progression." (PMID 40149989, 2025). "And EVs secreted by chemotherapy-resistant cells transport miR-21-5p (known to target tumor suppressors such as PDCD4) or PVT1, further inhibiting T cell activity." (PMID 40924501, 2025). "Further, the 3’ end of PVT1, which is lost during the translocation, codes for a tumor-suppressing micropeptide we named as Honeybadger (HNB)." (PMID 40027648, 2025). "For instance, using PVT1 ASO to target the lncRNA PVT1 has demonstrated the ability to suppress tumor cell proliferation in both laboratory and live models." (PMID 40149989, 2025). "Historically categorized as ‘non-coding’ RNA, our findings illuminates the dual functionalities of PVT1 as both oncogenic and tumor-suppressive via newly identified peptides, FFX and HNB, respectively." (PMID 40027648, 2025). "Our finding that MYC-AS1 acts as a tumor suppressor contrasts with the oncogenic role of PVT1, another non-coding RNA in the same genomic locus as MYC." (PMID 41190324, 2025). "Given the anti‐tumour activity of PVT1‐214 and its competitive suppression of miR‐128, it is evident that miR‐128 serves as a crucial anti‐tumour agent in tumour progression." (PMID 38506091, 2024).
tumor (continued). "Knockdown of ALKBH5 suppressed OV growth, colony formation, tumour formation and invasion, which were partially reversed by overexpression of PVT1." (PMID 38098223, 2024). "PVT1 upregulation promoted autophagy and tumor growth in NSCLC cells, with miR-216b interacting with PVT1 and Beclin-1." (PMID 39650649, 2024). "In a mouse xenograft model, the tumor volume has been seen to be significantly reduced by the deletion of PVT1 and miR-16-5p over-expression." (PMID 38294554, 2024). "Some studies have shown that PVT1 can interfere with the proliferation and spreading of tumor cells and the angiogenesis in tumor tissues by inhibiting miRNA." (PMID 39877345, 2024). "PVT1 is related to apoptosis, cell proliferation, lymph node invasion, metastasis and tumour prognosis in numerous malignancies." (PMID 38506091, 2024). "Most significantly, PVT1’s impact on metabolic reprogramming entails a reconfiguration of cellular metabolic routes, bolstering tumor growth and viability." (PMID 39286016, 2024). "A high PVT1 expression correlates with an advanced tumor stage, an increased likelihood of lymph node metastasis, and a reduced response to conventional therapies." (PMID 39452836, 2024). "PVT1 has already been demonstrated to play a significant role in tumor growth via the ceRNA mechanism." (PMID 38745179, 2024). "It has been found that lncRNA PVT1 is involved in tumour progression through interaction with miR‐195‐5p in endometrial cancer." (PMID 38098223, 2024). "PVT1 is another lncRNA linked to the etiology of CRC; its upregulation affects the downregulation of miR-16-5p, a key tumor suppressor in CRC." (PMID 38294554, 2024). "This metabolic flexibility enables tumor cells to endure metabolic stress, with PVT1 playing an indispensable role in this adaptive survival strategy." (PMID 39286016, 2024). "PVT1 has been shown to act as a molecular sponge for tumor-suppressive miRNAs, such as miR-195 and miR-29, thereby disrupting their tumor-suppressive functions." (PMID 39452836, 2024). "Patients with advanced tumor stage and metastasis were more likely to have elevated levels of PVT1 and CCAT1." (PMID 36624401, 2023). "Functional inactivation of PVT1 can alleviate chemoresistance and suppress carcinogenesis and tumor progression." (PMID 36524545, 2023). "The cell line with stable knockdown of PVT1 has significantly lower tumor diameter and weight than the control group." (PMID 36941464, 2023). "High lncRNA PVT1 expression was correlated with a poorer prognosis, the degree of tumor differentiation, distant metastasis, and disease stage in patients with OS." (PMID 37371065, 2023). "As the results indicated in functional and clinical analysis, PVT1 was involved in tumor progression and chemoresistance." (PMID 37202742, 2023). "The tumor-suppressor role of the PVT1 promoter was confirmed by an in vitro cell growth competition assay and an in vivo subcutaneous xenograft assay." (PMID 38933287, 2023). "Overexpression of PVT1 in vitro promoted cell proliferation, migration and invasion, and promoted tumor growth in vivo." (PMID 36941464, 2023). "The lncRNA PVT1/hsa-miR-16-5p/CASP6/CASP8 regulatory axis plays an vital role in regulating the anti-tumor immune responses for PAAD." (PMID 36882663, 2023). "In summary, we constructed a comprehensive ceRNA network characterized by a tumor invasion phenotype and identified a PVT1/DUSP13 axis featured with lipid regulatory potential, immune properties, and abnormal methylation states in patients with HCC and MVI." (PMID 36524545, 2023). "Comparing ESCC tissues to non-tumor tissues, we found significant upregulation of PVT1, CCAT1, and c-MYC." (PMID 36624401, 2023). "Immunofluorescence staining confirmed that PVT1 inhibition increased the number of tumor-infiltrating CD8+ T cells." (PMID 36894542, 2023).
tumor (continued). "In another example, COSMIC fusion PVT1:MYC was originally identified by STAR-Fusion in 20 samples (14 TCGA tumor, 1 TCGA normal, and 5 GTEx samples)." (PMID 37323575, 2023). "Overexpression of PVT1 in vitro promotes cell proliferation, migration and invasion, and promotes tumor growth in vivo." (PMID 36941464, 2023). "Results showed that PVT1 expression was significantly increased with tumor grade in both three independent cohorts." (PMID 37202742, 2023). "Our results indicated that the combination therapy comprising anti-PD1 and ASO PVT1 effectively eliminated CSCs to inhibit tumor growth and metastasis, and activated the tumor immune response to increase the recruitment of CD8+ T cells into tumor tissues." (PMID 36894542, 2023). "PVT1, a previously uncharacterized lncRNA, was identified as a critical regulator involved in multiple functions in tumor, including cell proliferation, cell motility, angiogenesis and so on." (PMID 37202742, 2023). "To further evaluate the tumorigenic effect of lncRNA PVT1 in vivo, we constructed a xenograft tumor model of A431 cSCC cells in nude mice." (PMID 36944636, 2023). "The results were consistent with existing findings on the major physiological function of PVT1 in tumor development." (PMID 37202742, 2023). "By contrast, PVT1 overexpression resulted in a decrease in necroptotic cell death events, thus promoting tumor progression." (PMID 37263709, 2023). "Since Pvt1 expression is augmented in tumour-infiltrated G-MDSCs more than in splenic G-MDSCs, the hypoxic conditions in TME are considered to trigger such a phenomenon." (PMID 36817434, 2023). "Histology demonstrated a higher rate of orthotopic tumor formation in the control group than in the PVT1 KD group." (PMID 36894542, 2023). "PVT1 inhibition eliminates CSCs, prevents metastasis, and stimulates anti-tumor immunity, while inhibiting HNSCC growth." (PMID 36894542, 2023). "In summary, our findings are important to develop new combination treatments for HNSCC that involve targeting PVT1 to eliminate CSCs, prevent metastasis, and activate the intrinsic immune responses of tumor cells." (PMID 36894542, 2023). "These miRNAs act as tumor suppressors, and PVT1 sponging them induces the expression of their target gene, NOP2 nucleolar protein (NOP2), a metastasis-related protein." (PMID 36831169, 2023). "In comparison to the normal group, the tumor group’s expression of PVT1 was considerably higher (p = 0.0096 < 0.05)." (PMID 37255541, 2023). "Histological examination demonstrated that PVT1 inhibition inhibited tumor cell numbers, areas, and invasiveness." (PMID 36894542, 2023). "This study demonstrated that PVT1 expression strongly correlated with tumor progression and chemo-resistance." (PMID 37202742, 2023). "The direct interaction between lncRNA PVT1 and 4EBP1 can lead to malignant transformation of cSCC cells, thereby inducing tumor progression." (PMID 36944636, 2023). "PVT1 expression levels in xenograft tumor tissues were assessed by RT-qPCR, and were found to be decreased in the sh-PVT1#3 group." (PMID 36944636, 2023). "According to PVT1 function in tumor stemness and metastasis, we assessed PVT1 as a potential HNSCC therapeutic target in an immunocompetent tumor immune microenvironment." (PMID 36894542, 2023). "Half the mice (n = 6) were euthanized after 4 wk to capture earlier effects of Pvt1 expression differences (mid-point of tumor growth as determined from pilot studies) and the remaining six mice were euthanized at 8 wk when they were moribund." (PMID 35820706, 2022).
tumor (continued). "We further showed that knockdown of PVT1 suppressed tumor cell proliferation and metastasis in vitro and in vivo, while ectopic expression of PVT1 increased tumor growth and migration, which were rescued by silencing of either CypB or STAT3." (PMID 36266267, 2022). "In vivo, PVT1 silencing repressed the tumor growth of SUP-B15 cells and reduced the expression of MAML3." (PMID 35152842, 2022). "It has been clarified that the PVT1 expression in many malignant tumor cell lines and tumor tissues is higher than that in normal tissues including GC and colorectal cancer." (PMID 35664988, 2022). "PVT1, LUCAT1, and LINC00982 thus represent potential diagnostic biomarkers capable of distinguishing between tumor and non‐tumor tissue with high sensitivity and specificity." (PMID 35441392, 2022). "Consistently, the weights of tumor tissues formed by sh-PVT1 transfected SUP-B15 cells were also lowered compared to that in the sh-NC group." (PMID 35152842, 2022). "Knockdown of PVT1 led to inhibition of tumor cell migration in accordance with the result of the wound-healing assay." (PMID 35664988, 2022). "PVT1 lncRNA was chosen because its expression levels indicated oncogenic activity, and the difference in expression between tumor and non‐tumor tissue was the most significant." (PMID 35441392, 2022). "In conclusion, various studies have demonstrated that both lncRNA PVT1 and circPVT1 are crucial for tumor development." (PMID 36379920, 2022). "MiR-134-5p, which directly target Stat3, is down-regulated in co-cultured MSCs, leading to tumor-like transformation of MSCs by enhancing Pvt1 expression, representing novel targets for therapeutic intervention of malignant diseases." (PMID 36295083, 2022). "In our study, we found that PVT1 expression is increased in tumor samples and that it correlates with increased MYC expression." (PMID 36139061, 2022). "Long noncoding RNA (lncRNA) is also implicated in PDAC, especially for the lncRNA plasmacytoma variant translocation 1 (PVT1), which is closely associated with tumor progression and chemoresistance to gemcitabine in pancreatic malignancy." (PMID 36292753, 2022). "Reinforcement of lncRNAs and microRNAs that can negatively regulate c-Myc expression such as LINC00261, Pvt1, MiR-145, MiR-494, and Let-7a seems to be a new and effective method to inhibit tumor cells proliferation and prevent cancer progression." (PMID 34978469, 2022). "Overexpression of ATAD2 and PVT1 in 8q24.13, RAD54B, LAPTM4B, and RRS1 in 8q21.13 were reported to be associated with tumor proliferation and progression of HCC." (PMID 36010950, 2022). "For example, tumor tissues with high PVT1 expression are resistant to GEM, cisplatin, adriamycin, and other chemotherapy drugs." (PMID 36195846, 2022). "Recent research has indicated that PVT1 was frequently upregulated in various tumors and promoted tumor progression by promoting the proliferation, migration and some other signaling pathways." (PMID 35256612, 2022). "Another lncRNA associated with the pathogenesis of CRC is plasmacytoma variant translocation 1 (PVT1); its up-regulation influences the down-regulation of miR-16-5p, which plays a significant role as a tumor suppressor in CRC." (PMID 36362222, 2022). "To date, most studies focusing on PVT1 reported its oncogenic function were exerted mainly through sponging tumor suppressive microRNAs." (PMID 36266267, 2022).